PDK4 (pyruvate dehydrogenase kinase 4)
Diseases named in the same sentence as PDK4 in open-access papers (continued):
Sharing a sentence is not in itself a finding about the gene and the disease.
Sepsis (14 papers, 2016 to 2026). Sepsis is defined as life-threatening organ dysfunction caused by a dysregulated host response to infection. "Other studies have substantiated that miR-195-5p is overexpressed in lung tissues of sepsis rats, and the up-regulation of cancer susceptibility candidate 9 (CASC9) improves sepsis-induced acute lung injury (ALI) by inactivating the miR-195-5p/PDK4 axis." (PMID 34790697, 2021). "This is especially true in the setup of acute inflammation, characteristic in critical illness in humans and in experimental sepsis models which is associated with enhanced expression of pyruvate dehydrogenase kinase 4 (PDK4), inactivating pyruvate dehydrogenase complex (PDC)." (PMID 27974893, 2016). "CEBPD and PDK4 were significantly upregulated in the sepsis group (L group), but downregulated in the imatinib group (M group), consistent with our sequencing results." (PMID 40524944, 2025). "In vehicle-pretreated sepsis mice, we found that there is an increased expression of cardiac Pdk4, a negative regulator of PDH." (PMID 39951524, 2025). "In summary, our findings in this report reveal a previously unrecognized role of myocardial PDK4 in mediating sex-based differences in cardiac outcomes during acute inflammatory challenges such as sepsis." (PMID 40626362, 2025). "Our histology indicated that PDK4 was elevated in patients with sepsis but was reduced when imatinib was administered." (PMID 40524944, 2025). "This study uncovers critical insights into mitochondrial signaling via PDK4 as a key contributor to sex-specific cardiac outcomes in response to sepsis or severe infections." (PMID 40626362, 2025). "PRKCA promotes mitochondrial autophagy via the miR-15a-5p/PDK4 axis to alleviate sepsis-induced ALI." (PMID 39667201, 2024). "Additionally, we found that the expression of CCAAT/enhancer-binding protein delta (CEBPD) and pyruvate dehydrogenase kinase 4 (PDK4) increased in the sepsis group but decreased in the imatinib group." (PMID 40524944, 2025). "Additionally, CASC9 and TUG1 alleviated the sepsis-induced ALI via affecting the miR-195-5p/PDK4 axis and miR-34b-5p/GAB1 axis." (PMID 34126975, 2021). "However, during sepsis, PDK4 is significantly upregulated in males, disrupting glucose and fatty acid metabolism, increasing ROS production, impairing mitochondrial structure and function, inhibiting mitophagy, and exacerbating cardiac inflammation, ultimately leading to heart failure." (PMID 40626362, 2025). "Moreover, miR-195-5p, which is generally involved in inducing and worsening ALI triggered by sepsis through inhibition of PDK4, could be stopped and downregulated by lncRNA CASC9." (PMID 36012630, 2022). "In sepsis-induced acute lung injury (SI-ALI), PDK4 hyperactivation drives excessive lactate production in epithelial cells, triggering AARS1/HDAC9-mediated LPCAT2 lactylation." (PMID 41057687, 2025). "PDK4 is upregulated in cardiac tissue from male mice after cecal ligation and puncture–induced (CLP-induced) sepsis." (PMID 40626362, 2025). "During sepsis, GLUT4 was down-regulated and PDK4 was up-regulated in cardiac tissues, which resulted in the inhibition of glucose metabolism, further aggravated the impairment of myocardial energy production and promoted the occurrence and development of cardiac injury in sepsis." (PMID 38641695, 2024).
cardiac hypertrophy (13 papers, 2011 to 2025). "In fact, Pdk4 was also reduced in Gadd45a KO mice, and reduced PDK4 activity in cardiac cells is often accompanied by depressed cardiac performance, cardiac hypertrophy and heart failure." (PMID 40301189, 2025). "It has also been reported that progesterone can induce the expression of PDK4 in cardiomyocytes and increased level of PDK4 in the third trimester of pregnancy further leads to cardiac hypertrophy during pregnancy." (PMID 34517782, 2021). "Recently, studies have reported that SIRT1 contributes to cardiac metabolism by activating PGC‐1α and pyruvate dehydrogenase kinase 4 (PDK4) expressions during cardiac hypertrophy." (PMID 32757458, 2020). "Recent data have demonstrated NF-κB activation resulted in reduced PGC-1α and Pyruvate dehydrogenase kinase 4 (PDK4) expression, contributing to cardiac metabolism in the process of cardiac hypertrophy." (PMID 25738576, 2015). "Under certain circumstances, such as cardiac hypertrophy or heart failure, reliance on the glycolytic pathways is increased due to the downregulation of PDK4 activity." (PMID 21625432, 2011). "Pyruvate dehydrogenase kinase 4 (PDK4) inhibition by nuclear factor-κB (NF-κB) is related to a shift towards increased glycolysis during cardiac pathological processes such as cardiac hypertrophy and heart failure." (PMID 21625432, 2011). "Especially, a role of PDK4 in cardiac hypertrophy and dilated cardiomyopathy has been reported." (PMID 29016649, 2017). "In cardiac cells exposed to TNF-α, the inhibition of PDK4 expression by NF-κB is related to the shift towards increased glycolysis that is observed during cardiac pathological processes induced by pro-inflammatory stimuli, such as cardiac hypertrophy and heart failure." (PMID 21625432, 2011). "We suggested that DAPA mediated the Plin5/PPARα signal axis, and ultimately affected the expression level of PDK4 and HMGCS2, myocardial cell metabolism, and relieve the pathological progression of cardiac hypertrophy." (PMID 34630108, 2021). "Free carnitine supplementation failed to rescue cardiac hypertrophy or to modulate gene expression of pyruvate dehydrogenase kinase 4, pathological remodeling markers, mTor, and myomitokines in Cpt2M−/− mice." (PMID 33757734, 2021). "We demonstrated that DAPA could activate the Plin5/PPARα signaling pathway and further significantly promoted the expressions PDK4 and HMGCS2 in cardiac hypertrophy." (PMID 34630108, 2021).
colon carcinoma (13 papers, 2017 to 2023). "Overexpression of PDK3 and PDK4 was shown to be associated with drug resistance and early recurrence in colon cancer cells." (PMID 28505181, 2017). "Up-regulation of PDK4 enhances the resistance of hepatocytes and colon cancer cells to chemotherapy-induced toxicity, while down-regulation of PDK4 enhances chemotherapy-related cell damage." (PMID 33739396, 2021). "PDK4 is up-regulated in normal mucosa of patients with colorectal cancer (CRC), and down-regulation of PDK4 in human colon cancer cells reduces cell migration and invasion, and increase cell apoptosis." (PMID 33739396, 2021). "Up-regulation of PDK4 increased the resistance of hepatocytes and colon cancer cells against chemotherapy-induced toxicity, whereas knockdown of PDK4 enhanced chemotherapy-associated cell damage." (PMID 30808993, 2019). "Research studies have verified that PDK4 methylation could display the oncogenic roles in colon cancer." (PMID 36003495, 2022). "The role of PDK4 in colon cancer metastasis is also reported." (PMID 34181336, 2021).
heart failure (13 papers, 2011 to 2025). Inability of the heart to pump blood at an adequate rate to meet tissue metabolic requirements. "Cardiac-specific overexpression of pyruvate dehydrogenase kinase 4 (PDK4) in transgenic mice has been shown to decrease glucose oxidation and increase fatty acid catabolism, and predispose animals to heart failure." (PMID 23951293, 2013). "Reduced glucose oxidation through increased PDK4 activity has been hypothesized to be involved in human heart failure associated with obesity and diabetes." (PMID 40686503, 2025). "Based on these findings, PDK4 inhibitors have been produced as putative treatments for heart failure with reduced ejection fraction." (PMID 40686503, 2025). "PDK4 is highly expressed in hearts and is upregulated in failing hearts, suggesting that PDK4 inhibition is a potential heart failure treatment." (PMID 38201291, 2023). "Then, we evaluated the efficacy of novel PDK4 inhibitor candidates in the treatment of heart failure." (PMID 38201291, 2023). "To establish a new, safe treatment for heart failure by inhibiting PDK4 activity, we searched for more active PDK4 inhibitors that are not structurally related to DCA or any other existing drugs." (PMID 38201291, 2023). "As PDK4 is a major cardiac regulatory kinase isoform that reversibly inactivates PDH, decreased PDK4 expression facilitates a greater capacity for activation of PDH in the heart failure group." (PMID 30881593, 2019). "As we did not measure activity or abundance of Lon protease, the role of this enzyme in this context in vitro or on the decreased PDK4 seen in our heart failure group is currently unclear, but is an important focus in our ongoing studies on PDK4." (PMID 30881593, 2019). "Although increased PDH activity has been reported in the ischemic porcine heart, decreased PDH activity with increased PDK4 has been reported in a porcine model of pacing-induced, early heart failure." (PMID 30881593, 2019). "PDK3 expression was not measured due to low expression in the heart, whereas mRNA expression changes in PDK2 and PDK4 isoforms have been reported for human heart failure." (PMID 30881593, 2019). "Since exacerbation of both influenza severity and heart failure appear to converge on PDK4, we hypothesized that they have a common pathogenetic mechanism." (PMID 38201291, 2023). "The heart expresses PDK4 highly, and during heart failure, PDK4 is upregulated." (PMID 38201291, 2023). "Since 8, which had the highest in vivo PDK4 inhibitory capacity, induced the highest EF recovery, the strength of PDK4 activity might predict the prognosis of heart failure." (PMID 38201291, 2023). "As we observed a marked decrease in PDK4 expression in our heart failure group, we undertook a preliminary, limited study of whether PDK expression could be modulated in cultured human ventricular cardiomyocytes induced to hypertrophy with Ang II." (PMID 30881593, 2019). "Thus, we focused on vitamin K3 and used its framework as a new PDK4 inhibitor skeleton to synthesize new PDK4 inhibitors that show higher activity than the existing PDK4 inhibitor, dichloroacetic acid, and tested their cardioprotective effects on a mouse heart failure model." (PMID 38201291, 2023). "For example, scRNA-seq has revealed a shift from fatty acid oxidation to glycolysis in cardiomyocytes during heart failure, with changes in key enzymes such as CPT1B and PDK4 affecting circulating metabolite levels (e.g., lactate, acylcarnitines)." (PMID 41403700, 2025). "Since E2F1 plays an important role in cardiac myocyte growth and is also involved in metabolism regulation through PDK4 modulation, targeting this transcription factor could provide us with an effective therapy for treating detrimental left ventricular hypertrophy leading to heart failure." (PMID 21625432, 2011). "Considering heart failure (HF) is common in ACM patients, it may seem counterintuitive that Pdk4 expression was significantly down-regulated in Val-treated Dsg2mut/mut mice." (PMID 36430389, 2022).
heart failure (continued). "In addition, the mRNA of PDK4 was also reported to be increased along with PGC-1α after exercise in muscle tissue and downregulated in cardiac tissue during heart failure." (PMID 29190898, 2017). "Since PDK4 inhibition is a new treatment target for heart failure that existing treatment regimens do not cover, patients who respond poorly to those medications may be saved using compounds tested in the present study." (PMID 38201291, 2023). "Nor is nutrient deprivation, as PDK4 expression was low in the heart failure group." (PMID 30881593, 2019). "Thus, PDK4 inhibitor 8 may be used to treat heart failure regardless of cardiac remodeling." (PMID 38201291, 2023). "Cardiac remodeling in heart failure with preserved ejection fraction (HFpEF) varies from patient to patient, and it is currently recommended that treatment be tailored to the patient’s condition; however, PDK4 Inhibitor 8 could be administered regardless of individual cardiac remodeling." (PMID 38201291, 2023).
Hyperglycemia (13 papers, 2013 to 2025). An increased concentration of glucose in the blood. "Notably, the dysregulated genes Cpt1a, Foxo1 and Pdk4 also appeared in the network of top 10 upregulated and downregulated mRNAs, indicating that these mRNAs might associate with hyperglycemia and T2D in GK rats at the age of 3 and 4 weeks." (PMID 32095365, 2020). "Overall, Decr1 may be a positive regulator of PDK4, leading to hyperglycemia‐induced cardiomyocyte injury." (PMID 40052435, 2025). "Hyperglycemia alone, i.e., in an insulin deficient and non-obese context, has been shown to rapidly increase cardiac expression of Pdk4 and Ucp3, and to provoke metabolic inflexibility and cardiac dysfunction in mice." (PMID 37626210, 2023). "Metabolic analyses reveal that deletion of the Pdk4 gene had better improvement in hyperglycemia and glucose tolerance than knockout of the Pdk2 gene whereas the Pdk2 gene deletion showed better insulin tolerance as compared to the Pdk4 gene inactivation on the Irs1/2 knockout genetic background." (PMID 23940800, 2013).
prostate carcinoma (13 papers, 2015 to 2025). A carcinoma that arises from epithelial cells of the prostate gland. "One study insisted, AMPK/GSK3β/β-catenin cascade triggered KIAA1199 over-expression may promote migration and invasion in anoikis-resistant prostate cancer cells by increasing PDK4-associated metabolic reprograming, which may provide a novel therapeutic target for the prostate cancer." (PMID 33194340, 2020). "Particularly, consistent with the lacking the Warburg effect, it had been reported that the expression of PDK4 is significantly down-regulated in prostate cancer and is related to tumor recurrence, and drug resistance." (PMID 37863991, 2023). "For example, LncRNA PCAT19 plays an important role in the snp-mediated promoter-enhancer conversion mechanism in the process of regulating prostate cancer and adjusts the proliferation of laryngeal cancer cells by regulating the miR-182/PDK4 axis." (PMID 35854199, 2023). "CEMIP has been shown to enhance PDK4-mediated metabolic reprogramming to promote metastasis of prostate cancer." (PMID 35543351, 2022). "Correlation between clinical and pathological variables and PDK1, PDK2, PDK3 and PDK4 protein expression in prostate cancer." (PMID 35692804, 2022). "CEMIP promoted PDK4 to enhance the metabolic reprogramming and induce prostate cancer cell metastasis." (PMID 35543351, 2022). "This is the case for prostate cancer, the most common cancer in men, and makes PDK4 an interesting therapeutic target." (PMID 33384955, 2020). "Pyruvate dehydrogenase kinases such as PDK3 and PDK4 are important markers in glycolysis, have been reported to be used to predict the recurrence in prostate cancer, this might be relevant with the elevated level of lactate and the activation of TNF pathway." (PMID 39811936, 2025). "Pyruvate dehydrogenase kinase 4 (PDK4) could also be a potential prognostic target in prostate cancer." (PMID 34638309, 2021). "Similarly, reducing PDK4 directly through shRNA resulted in increased tumor free survival of mice bearing prostate cancer cell xenografts." (PMID 26576332, 2015). "Furthermore, the depletion of CEMIP in prostate cancer cells reduces the expression of pyruvate dehydrogenase kinase isoform 4 (PDK4) and lactate dehydrogenase A (LDHA), enzymes important for efficient glycolysis in tumor cells, thereby decreasing cellular pyruvate, lactate, and ATP levels." (PMID 36291875, 2022). "Transcriptomic and proteomic analyses in prostate cancer (PCa) reveal high TCA/OXPHOS activity and low PDK4 expression in low STAT3 tumors." (PMID 32323921, 2020). "Similarly, knockdown of PDK4 increases lipogenesis and has been reported to increase HCC growth rates, with similar findings in prostate cancer." (PMID 36980540, 2023).
atherosclerosis (11 papers, 2015 to 2024). A disease characterized by the build-up of fatty material and calcium deposition in the arterial wall resulting in partial or complete occlusion of the arterial lumen. "Previous studies suggested that PDK4 is increased in the calcified vessels of patients with atherosclerosis and is closely associated with mitochondrial function, but the precise regulatory mechanisms remain largely unknown." (PMID 33203874, 2020). "The functions of PDK4 are all focused on the involvement of lipid metabolism in the process of atherosclerosis." (PMID 38650649, 2024). "Studies show that PDK4 expression is heightened in calcified blood vessels of atherosclerosis patients." (PMID 38547044, 2024). "In atherosclerosis, high expression of PDK4 promotes vascular calcification, and its absence also inhibits platelet function and arterial thrombosis." (PMID 38671369, 2024). "Since PDK4 expression is increased in calcified vessels of patients with atherosclerosis, we explored whether PDK4 promotes the expression of several osteogenic genes." (PMID 29348870, 2017).